DRAM1 (DNA damage regulated autophagy modulator 1)
Diseases named in the same sentence as DRAM1 in open-access papers (continued):
Sharing a sentence is not in itself a finding about the gene and the disease.
infection (13 papers, 2012 to 2023). The state of being infected such as from the introduction of a foreign agent such as serum, vaccine, antigenic substance or organism. "In cell death-related KEGG pathways, Dram1 deficiency affected the regulation of programmed cell death during infection, resulting in enhanced expression of genes involved in lytic forms of cell death." (PMID 32332700, 2020). "Strikingly, we found that Dram1 deficiency leads to increased inflammatory caspase activity and gasdermin-dependent pyroptotic cell death during infection." (PMID 32332700, 2020). "By in vivo imaging, we observed that Dram1-deficient macrophages fail to restrict Mm during early stages of infection." (PMID 32332700, 2020). "RNA sequencing revealed major effects of Dram1 deficiency on metabolic, immune response, and cell death pathways during Mm infection, and only minor effects on proteinase and metabolic pathways were found under uninfected conditions." (PMID 32332700, 2020). "Therefore, we conclude that DRAM1 loss-of-function impairs the ability of macrophages to control Mm infection." (PMID 36980169, 2023). "Considering that Dram1 is a downstream target of the Tlr-Myd88-NF-κB signaling pathway, we also investigated if Dram1 could rescue the infection susceptibility of myd88 mutants." (PMID 38264729, 2023). "We show that Dram1 deficiency reduces autophagic targeting of Mm and acidification of Mm-containing vesicles, ultimately resulting in pyroptotic cell death of infected macrophages and increased extracellular growth of mycobacteria during early stages of the infection." (PMID 32332700, 2020). "Based on previous results in a zebrafish infection model, we have proposed that DRAM1 is a host resistance factor against intracellular mycobacterial infection." (PMID 36980169, 2023). "While DRAM1–Mm colocalised from the start of the infection, LysoTracker–Mm colocalisation sharply increased from low levels to approximately 50% at 120 min." (PMID 36980169, 2023). "Here, we show the progression of the colocalisation of DRAM1 with Mm over the course of infection, and study this in relation to LC3, LysoTracker and LAMP1 patterns, as markers for autophagosomes and (endo)lysosomes." (PMID 36980169, 2023). "Dram1 is known as an infection-inducible protein that protects the zebrafish host against Mm infection, similar to Optn and p62." (PMID 38264729, 2023). "In conclusion, Dram1 protects against Mm infection by promoting the interaction of Lc3 with Mm and the acidification of Mm-containing vesicles, even in the absence of both Optn and p62." (PMID 38264729, 2023). "Damage-Regulated Autophagy Modulator 1 (DRAM1) is an infection-inducible membrane protein, whose function in the immune response is incompletely understood." (PMID 36980169, 2023). "Next, we analysed the effect of DRAM1 knockdown on Mm infection at 120 min post infection, the time point at which DRAM1–Mm colocalisation events were most frequent." (PMID 36980169, 2023). "We then continued to study DRAM1 localisation during Mm infection and followed the acidification of Mm-containing vesicles by LysoTracker staining." (PMID 36980169, 2023). "DNA damage-regulated autophagy modulator 1 (DRAM1) is increased after infection with Mycobacterium marinum (M.m) closely related to M. tb, which can promote the elimination of mycobacteria through selective autophagy." (PMID 36992931, 2023). "Messenger RNA levels of the autophagy-related genes were significantly elevated at most of the timepoints after infection, except for some genes (Bcl-2, Atg5, Atg12, DRAM1, and VMP1) whose transcription levels declined at 7 dpi." (PMID 33600403, 2021). "Together, these data demonstrate that Dram1 is necessary for macrophages to contain the infection and prevent extracellular bacterial growth." (PMID 32332700, 2020). "In conclusion, restriction of mycobacteria in infected macrophages during the early stages of infection requires functional Dram1." (PMID 32332700, 2020).
infection (continued). "Together, these studies indicate that DRAM1/Dram1 expression levels can have a major impact on cell death processes during infection, with different outcomes depending on the cell type and infectious agent." (PMID 32332700, 2020). "Analysis of the mutant fish showed that Dram1 is required for maturation of Mm-containing vesicles and for macrophages to restrict Mm infection." (PMID 32332700, 2020). "An attractive target for drug development is the process mediated by the infection-inducible autophagy modulator Dram1, which was discovered in zebrafish." (PMID 33138004, 2020). "Dram1 is an autophagy modulator that is induced during infection of zebrafish by the MYD88-NFκB-dependent signaling pathway, which occurs downstream of pathogen recognition by Toll-like receptors." (PMID 28698482, 2017). "Several factors have be shown to be involved in the containment of infection by macrophages in zebrafish, including tumor necrosis factor (Tnf), autophagy components (P62/Sqstm1 and Dram1), and a macrophage-specific perforin (Mpeg1)." (PMID 26324465, 2016). "Infection of human macrophages further placed NFκB upstream of DRAM1 gene expression and demonstrated colocalization of DRAM1 protein with Mtb." (PMID 26324465, 2016). "Since exosomes are crucial for communication between immune cells, this might point to an unexplored role for DRAM1 in the intercellular propagating of signals during infection." (PMID 36980169, 2023). "Therapeutic strategies targeting DRAM1 might be more broadly applicable against other intracellular pathogens, considering our recent results that DRAM1 also protects against infections with Salmonella enterica serovar Typhimurium and Aspergillus fumigatus." (PMID 36980169, 2023). "However, the host-protective role of Dram1 is clearly demonstrated by the results showing that Dram1 overexpression can rescue the infection phenotype of optn/p62 double mutants, as well as restore Lc3-Mm colocalization in these mutants." (PMID 38264729, 2023). "We aimed to identify changes in the gene expression network caused by the absence of functional Dram1, rather than by the increased level of infection in mutants." (PMID 32332700, 2020). "Besides infection, DNA-damage, and interference with energy metabolism, it remains to be further investigated which stress factors can activate DRAM1/Dram1 in vitro and in vivo." (PMID 32332700, 2020). "Overexpression of Dram1 by mRNA injection was found to result in increased lysosomal acidification of M. marinum containing compartments and to improve resistance of zebrafish embryos to the infection." (PMID 28698482, 2017). "Furthermore, upon DRAM1 knockdown, the Mm infection rate increased." (PMID 36980169, 2023). "Having determined the requirements of DRAM1 for Mm’s colocalisation with LysoTracker, LC3 and LAMP1, we wished to understand whether this role of DRAM1 in Mm vesicle trafficking impacts the susceptibility of RAW 264.7 macrophages to Mm infection." (PMID 36980169, 2023). "Knockdown of Dram1 also decreased colocalization of LC3 and Mm in RAW 264.7 macrophages, reduced the acidification of Mm-containing compartments, and impaired the control of infection." (PMID 38264729, 2023). "In the absence of Dram1, infected macrophages rapidly become overburdened by the bacteria and initiate pyroptotic cell death, resulting in increased dissemination of the infection." (PMID 32332700, 2020). "However, due to the lack of antibody tools for zebrafish, we have not been able to study how DRAM1 colocalises with mycobacteria, autophagosomes and lysosomes during the course of infection." (PMID 36980169, 2023). "In addition, it is not clear whether DRAM1-mediated autophagy enhancement during infection requires SLR activity." (PMID 38264729, 2023). "In agreement, overexpression of Dram1 in zebrafish was found to increase the number GFP-Lc3 punctae, even in the absence of infection, suggesting that more autophagosomes were formed under these conditions." (PMID 38264729, 2023).
bacterial infection (1 paper, 2023). "DRAM1 was also in close proximity to FAM49B (related to bacterial infection), THBS1 (related to autophagy), TAGLN2 (related to phagocytosis), and PDIA3 (related to autophagy), which displayed higher expression levels in and around the cell nucleus." (PMID 37919720, 2023). "We also discovered that DRAM1 is co-expressed with GAPDH, a gene encoding a key enzyme in the glycolytic pathway that regulates autophagy in response to bacterial infection." (PMID 37919720, 2023). "DRAM1 was previously revealed to regulate autophagy against bacterial infection in macrophages." (PMID 37919720, 2023). "This further strengthens regulatory function of DRAM1 in autophagy and bacterial infection." (PMID 37919720, 2023).
DRAM1 also shares sentences with these, for which no sentence is quoted: viral infection (3 papers); bladder cancer (2); Crohn disease (2); HIV-1 infection (2); maturity onset diabetes (2); non-small cell lung carcinoma (2); ulcerative colitis (2); AIDS (1); autoimmune disorders (1); B-cell lymphomas (1); basal cell carcinoma (1); breast invasive carcinoma (1); breast tumor (1); cardiac hypertrophy (1); degenerative diseases (1); Diabetes (1); Ewing sarcoma (1); fetal growth restriction (1); glaucoma (1); head and neck tumor (1); Hepatic steatosis (1); Hypertension (1); infectious disease (1); ischemia (1); liver cancer (1); lung disorder (1); lymphoma (1); mesenchymal tumors (1); multiple sclerosis (1); Mycobacterium infection (1).
A further 8 diseases each share a sentence with DRAM1 in 1 paper.